NPDC1 (neural proliferation, differentiation and control 1)
Description:
Suppresses oncogenic transformation in neural and non-neural cells and down-regulates neural cell proliferation. Might be involved in transcriptional regulation (By similarity).
Synonyms: NPDC-1; DKFZp586J0523; CAB-; CAB1; CAB; CAB-1
Tractability: Antibody: its Gene Ontology location is reachable by antibodies, with high confidence; UniProt predicts a signal peptide or a membrane-spanning region. PROTAC: ubiquitination databases record sites on it; its protein half-life has been measured.
Gene: Protein-coding gene on chromosome 9 (137,039,459 to 137,046,695, reverse strand). Ensembl gene ENSG00000107281.
Subcellular location: Membrane
Subcellular location (Human Protein Atlas): Nucleoplasm; Cytosol
Pathways (Reactome):
Immune System: Immunoregulatory interactions between a Lymphoid and a non-Lymphoid cell
Gene Ontology:
Molecular function: protein binding
Cellular component: plasma membrane; membrane
Genetic constraint (gnomAD): Loss-of-function variants: 15 observed, 19.36 expected, observed/expected ratio (o/e) 0.77, 90% interval 0.52 to 1.19. The synonymous counts are far from expectation, so gnomAD's model fits this gene poorly and the ratio says little. Missense variants: 368 observed, 264.1 expected, observed/expected ratio (o/e) 1.39, 90% interval 1.28 to 1.52. Synonymous variants: 149 observed, 107.9 expected, observed/expected ratio (o/e) 1.38, 90% interval 1.21 to 1.58.
Homologues: Orthologues: chimpanzee NPDC1 (93% identical), macaque NPDC1 (87% identical), dog NPDC1 (78% identical), mouse Npdc1 (75% identical), pig NPDC1 (70% identical), guinea pig NPDC1 (69% identical), zebrafish npdc1a (38% identical), tropical clawed frog NPDC1 (36% identical), zebrafish npdc1b (36% identical), Drosophila melanogaster CG44247 (28% identical), Caenorhabditis elegans cab-1 (22% identical).
Diseases named in the same sentence as NPDC1 in open-access papers:
NPDC1 is named in the same sentence as 12 diseases in open-access papers, as found by Europe PMC text mining. Sharing a sentence is not in itself a finding about the gene and the disease. The quoted sentences say what the papers report.
breast carcinoma (2 papers, 2007 to 2017). "Eight loci (PABPC4L, APBA2, FAM189A1, FUT7, ENTPD2, NPDC1, C9orf139 and L1CAM) were associated with risks for both breast cancer and ovarian cancer (P<0.05)." (PMID 28145423, 2017).
acute myeloid leukemia (1 paper, 2023). Acute myeloid leukemia (AML) is a group of neoplasms arising from precursor cells committed to the myeloid cell-line differentiation. "Despite being relatively less explored, NPDC1 has garnered attention due to its significant upregulation during acute myeloid leukemia (AML) relapse." (PMID 38023180, 2023).
COVID-19 (1 paper, 2023). A disease caused by infection with severe acute respiratory syndrome coronavirus 2. "For the first time, we reported elevated plasma NPDC1 and CHRDL1 in patients with COVID-19 with comorbidities." (PMID 37047248, 2023).
gastric cancer (1 paper, 2022). A primary or metastatic malignant neoplasm involving the stomach. "We screened eight DDR-related genes (ZBTB7A, POLQ, CHEK1, NPDC1, RAMP1, AXIN2, SFRP2, and APOD) to establish a risk model, which can predict the prognosis of gastric cancer patients and guide the clinical implementation of immunotherapy." (PMID 36578802, 2022).
Niemann-Pick disease type A (1 paper, 2019). Niemann-Pick disease type A is a very severe subtype of Niemann-Pick disease, an autosomal recessive lysosomal disease, and is characterized clinically by onset in infancy or early childhood with failure to thrive, hepatosplenomegaly, and rapidly progressive neurodegenerative disorders. "Niemann–Pick disease type C is clinically similar to Niemann-Pick disease type A, but is determined by mutations of a different gene (NPDC1, neural proliferation differentiation and control protein 1), coding a protein regulating endocytic transport in late endosomes and lysosomes." (PMID 31284408, 2019).
osteosarcoma (1 paper, 2025). A usually aggressive malignant bone-forming mesenchymal neoplasm, predominantly affecting adolescents and young adults. "CERS1, FABP3 and NPDC1 significantly propelled predictions towards high mitophagy, indicating these genes positively regulate mitophagy in osteosarcoma." (PMID 39834330, 2025). "Gene expression comparisons between groups corroborated these findings, demonstrating significantly higher expressions of CERS1, FABP3 and NPDC1 in high‐mitophagy osteosarcoma, whereas PLEKHF1 and LILRA2 were significantly less expressed." (PMID 39834330, 2025).
soft tissue sarcoma (1 paper, 2022). A malignant neoplasm arising from muscle tissue, adipose tissue, blood vessels, fibrous tissue, or other supportive tissues excluding the bones. "The NPDC1 gene is able to suppress oncogenic transformation in neural and nonneural cells and overexpressed in intraductal papillary mucinous neoplasms of the pancreas and soft tissue sarcoma." (PMID 35798703, 2022).
synucleinopathy (1 paper, 2025). A neurodegenerative disease that is characterized by the abnormal accumulation of aggregates of alpha-synuclein protein in neurons, nerve fibers or glial cells. "The protection of nigral DA neurons from α-syn PFF induced neurodegeneration in the transheterozygote state confirms a key role for the interaction of mGluR4 and Npdc1 in synucleinopathy." (PMID 40777374, 2025). "Since previous studies have disputed a role for PrPC in synucleinopathy, we focused on mGluR4 and NPDC1 here." (PMID 40777374, 2025).
Tumor (2 papers, 2007 to 2023). "Expression of the differentiation markers Npdc-1 and probasin were significantly decreased in the tumor, suggesting an inhibition of luminal cell differentiation." (PMID 17343742, 2007). "Tumor development in the LADY mouse is associated with an increased rate of epithelial proliferation at both six and 16 weeks, increased expression of progenitor cell markers (Notch-1, Nestin) and decreased expression of terminal differentiation markers (Npdc-1 and probasin)." (PMID 17343742, 2007).
NPDC1 also shares sentences with these, for which no sentence is quoted: Niemann-Pick disease type C (1 paper); ovarian carcinoma (1); prostate carcinoma (1).